INS (insulin)
Diseases named in the same sentence as INS in open-access papers (continued):
Sharing a sentence is not in itself a finding about the gene and the disease.
pancreatic cancer (continued). "In the fully adjusted models, initiation of OHG medications had a HR of 1.39 (95% CI, 0.86–2.27) and insulin had a HR of 2.84 (95% CI, 1.58–5.12) for developing pancreatic cancer." (PMID 37117188, 2023). "A nearest neighbor matching analysis was performed to investigate the effect of insulin therapy on the survival of pts with pancreatic cancer." (PMID 37297851, 2023). "We next created a composite measure of starting either OHG or insulin, which demonstrated a HR for pancreatic cancer of 1.99 (95% CI, 1.30–3.03)." (PMID 37117188, 2023). "In vitro studies have demonstrated that insulin can stimulate the growth of pancreatic tumor cells and that the proliferation of tumor cells is dependent on insulin dose." (PMID 36672448, 2023). "Although the link between sugar-sweetened beverages (SSB) and pancreatic cancer has been suggested for its insulin-stimulating connection, most epidemiological studies showed inconclusive relationship." (PMID 35463371, 2022). "We also concluded the current ways of lowering insulin levels and clinical advances targeting the insulin signal pathway in pancreatic cancer." (PMID 35252207, 2022). "KEGG analysis revealed their involvement in insulin signaling pathways, neurotrophin signaling pathways, and pancreatic cancer." (PMID 35408847, 2022). "Secreted substances from pancreatic cancer cells have been proposed to alter metabolism in skeletal muscle and induce peripheral insulin resistance and cachexia in skeletal muscle." (PMID 36355178, 2022). "Due to the low prevalence of pancreatic cancer in the whole population, insulin is safe for most diabetic patients." (PMID 35252207, 2022). "Studies have suggested an association between SSBs and pancreatic cancer, most probably due to SSB-induced rapid increase in blood sugar, which stimulates insulin secretion and cancer cell proliferation." (PMID 35463371, 2022). "Insulin has long been regarded as a promoter for cancer metabolism and proliferation in many types of cancer, including breast, prostate, colorectal and pancreatic cancer." (PMID 35252207, 2022). "Another study looked at how different pancreatic diseases (pancreatic cancer, pancreatitis, and benign tumors of the pancreas) affected glucose homeostasis and insulin secretion after a 50% partial pancreatectomy." (PMID 36422243, 2022). "In the pancreatic cancer microenvironment, pancreatic cancer cells and fibroblasts produce adrenomedullin to inhibit adipocyte response to insulin signals." (PMID 35252207, 2022). "This reciprocal relationship between cancer and insulin reveals that insulin plays an essential role in pancreatic cancer onset and development." (PMID 35252207, 2022). "Reduced insulin sensitivity was observed in pancreatic cancer patients’ muscle, adipose, and liver tissue, which is believed to result from exosomes secreted from pancreatic cancer cells." (PMID 35252207, 2022). "Currently, drugs treating insulin-related signal pathways receive poor clinical outcomes, which are due to drug intolerance and alternative signal pathway that drive pancreatic cancer cells to survive and proliferation." (PMID 35252207, 2022). "Insulin-induced PD-L1 expression seems to allow pancreatic cancer cells to suppress the proliferation of CD8+ T-cells, leading to immune evasion." (PMID 35954223, 2022). "Of great interest in this context, numerous studies have determined a possible link between insulin and immune evasion by pancreatic cancer cells." (PMID 35954223, 2022). "The intricate relationship between pancreatic cancer and insulin allows us to have a better understanding of the PDA initiation, metabolic reprogramming, development, chemoresistance, and metastasis." (PMID 35252207, 2022). "Overall, our data demonstrate that the in vitro achievement of insulin-producing cells as a result of ATRA-induced differentiation of precursors or pancreatic cancer cells is almost completely dependent from Vav1, whose expression is in turn regulated by ATRA." (PMID 33165749, 2021).
pancreatic cancer (continued). "We analyzed the infiltration of pancreatic cancer cells into pancreatic islets via double-immunolabeling of human pancreatic cancer tissues with insulin or glucagon and the pancreatic cancer cell marker cytokeratin 19 (CK-19) or Mucin-1 (MUC1)." (PMID 33440856, 2021). "Although most pancreatic cancer patients are treated with glucose-lowering drugs or insulin, it is still different from their natural physical condition, and insulin is also an essential factor in promoting the development of PC." (PMID 34090418, 2021). "In recent years, insulin has been found to affect the progression of pancreatic cancer at different stages." (PMID 34485124, 2021). "Through insulin-induced PD-L1 expression, pancreatic cancer cells suppress proliferation of CD8+ T-cells underscoring the potential of insulin to confer immune evasion through this immune checkpoint regulator." (PMID 34202040, 2021). "All-trans retinoic acid (ATRA) promotes the development and the function of insulin producing cells and induces partial differentiation of pancreatic tumor cells." (PMID 33165749, 2021). "Many of them are relevant to pancreas functions, including insulin processing, insulin receptor recycling, insulin glucose pathway, pancreatic cancer, etc." (PMID 34489404, 2021). "In our study, we explored a possible link between insulin and the immune evasion of pancreatic cancer cells." (PMID 34202040, 2021). "The patients with pancreatic cancer underwent pancreatic surgery in varying extent with changes and disruption of production of insulin in the pancreas." (PMID 33253318, 2020). "With the purpose of developing a more efficient pancreatic cancer gene therapy, a synthetic human insulin super-promoter (SHIP1) was designed to improve the activity and specificity of the human insulin promoter." (PMID 33381459, 2020). "Mice with reduced insulin had a significant decrease in the number of PanINs and pancreatic tumors when compared to controls." (PMID 33101198, 2020). "We also found alteration in AGE-RAGE signaling pathway, insulin resistance signaling pathway and prolactin signaling pathway, which were less discussed in pancreatic cancer." (PMID 31795960, 2019). "In the matured pancreas, the expression of PDX1 is restricted to insulin-producing β-cells, but is also found to be upregulated in pancreatic cancer." (PMID 31236113, 2019). "The Vascular Endothelial Growth Factor(VEGF) pathway is angiogenesis related, and the insulin-signaling pathway is studied for pancreatic cancer growth and metastasis." (PMID 31739607, 2019). "Most patients were receiving oral agents or insulin at the time of their pancreatic cancer diagnosis." (PMID 29682326, 2018). "For instance, when pancreatic cancer was induced in hamsters, the endocrine pancreas showed a decrease in insulin-producing cells and an increase in other hormonal cells." (PMID 29609556, 2018). "Concerning pancreatic cancer, studies have demonstrated that exposure to insulin results in a higher number of pancreatic cancer cells responding to low picomolar concentrations of neurotensin, a GPCR agonist." (PMID 29462993, 2018). "Among DM patients, 15 (16%) needed to change their DM therapy within 1 year of pancreatic cancer diagnosis: one patient (7%) switched to diet control as DM therapy, three (20%) switched to oral treatment and 11 (73%) switched to insulin." (PMID 29682326, 2018). "In turn, Karnevi provided molecular evidence that the decreased anticancer action of metformin in pancreatic cancer cells exposed to HG involved the insulin/insulin-like growth factor-1 (IGF1) pathway." (PMID 30217067, 2018). "In an effort to identify the effect of shTG2+shp53 pancreatic cancer cells on pancreatic β cells in vivo, we evaluated glucose and insulin tolerance in vivo." (PMID 29088786, 2017). "A recently published research suggests that stroma-derived IGFs can blunt the response to chemotherapy in pancreatic cancer via an IGF-insulin/IGF1R paracrine signaling axis." (PMID 28969062, 2017).
pancreatic cancer (continued). "Insulin, as well as glucose, is known to promote cell proliferation in pancreatic cancer cells contributing to chemoresistance." (PMID 29118444, 2017). "About 32% of all cancer cases and the majority of pancreatic cancer cases (63%) were diagnosed during the first year of insulin treatment." (PMID 28573394, 2017). "In the present study, we have investigated the mechanism of cytotoxicity of STZ in insulin-secreting pancreatic cancer cells (Rin-5F) at different doses and time intervals." (PMID 28845214, 2017). "For example, pancreatic cancer cells shed exosomes that can be internalized by β-cells to negatively impact insulin secretion and further pancreatic cancers." (PMID 27672367, 2016). "Preoperative localization of the insulin secreting pancreatic tumors is important for further effective surgical excision, which should be limited to the affected part of the pancreas." (PMID 27526057, 2016). "Several in vitro and in vivo studies have shown that pancreatic miRNA-375 directly targets PDK1, plays key roles in the glucose regulation of insulin gene expression and β-cell growth and is down-regulated in pancreatic carcinoma." (PMID 27276676, 2016). "For example, several studies reported that pancreatic miRNA-375, which directly targets PDK1, plays key roles in the glucose regulation of insulin gene expression and β-cell growth and was evidently downregulated in pancreatic carcinoma." (PMID 27276676, 2016). "Another interesting function of SCF is to regulate the differentiation of PANC-1 pancreatic cancer cells into insulin-producing cells." (PMID 25799412, 2015). "The present study examined the actions of insulin on cell viability across different stages of pancreatic cancer in vitro." (PMID 25373319, 2014). "It is therefore imperative to investigate the effects of insulin on different stages of pancreatic cancer progression." (PMID 25373319, 2014). "Activation of both insulin and IGF1 receptors has been implicated in pancreatic cancer progression and chemotherapy resistance." (PMID 25373319, 2014). "Complementary in vivo studies are urgently needed to assess the role of insulin and insulin signalling on pancreatic cancer progression." (PMID 25373319, 2014). "To set a baseline for our in vitro model of pancreatic cancer progression, we next sought to establish the effects of insulin on normal human pancreatic exocrine-ductal cells." (PMID 25373319, 2014). "In the present study, we examined the effects and mechanisms of insulin in three in vitro cell models designed to mimic the progression of pancreatic cancer in vivo." (PMID 25373319, 2014). "At the same time, insulin promotes pancreatic cancer in both epidemiologic and animal studies either directly or indirectly." (PMID 25090635, 2014). "Insulin-producing tumours of the pancreas and EAS have been previously reported to co-exist in multiple endocrine neoplasia type 1 (MEN1)." (PMID 24683485, 2014). "As an adjunct to our studies on the effects of insulin in pancreatic cancer cells, we compared native insulin to a short-acting insulin analogue (LisproTM) and a long-acting insulin analogue (GlargineTM) on the viability of PANC1 cells." (PMID 25373319, 2014). "For miR-375, in vitro and animal studies showed that pancreatic miRNA-375 directly targets PDK1, plays key roles in glucose regulation of insulin gene expression and β-cell growth and is down-regulated in pancreatic carcinoma." (PMID 25255814, 2014). "Our results indicate that metformin has direct anti-tumour activities in pancreatic cancer cells involving AMPKThr172 activation and suppression of the insulin/IGF signalling pathways." (PMID 23663483, 2013). "Here, we demonstrate that treatment of PANC-1 or MiaPaCa-2 pancreatic cancer cells with either rapamycin or active-site mTOR inhibitors suppressed S6K and S6 phosphorylation induced by insulin and the GPCR agonist neurotensin." (PMID 23437362, 2013).
pancreatic cancer (continued). "Hazard ratio of overall cancer and pancreatic cancer among exclusive users of insulin glargine vs. intermediate/long-acting human insulin (HI) users." (PMID 21738645, 2011). "Many experimental studies and observational studies support the biological plausibility of higher insulin concentrations and insulin resistance in promoting pancreatic cancer development." (PMID 18628761, 2008). "If this were to be the case, then reduction of interleukin-6 concentrations would be a prerequisite for the reduction of insulin resistance and fat oxidation in weight-losing pancreatic cancer patients." (PMID 15026790, 2004). "The authors noticed a significant connection between treatment with insulin and pancreatic cancer." (PMID 40299428, 2025). "The activation of the Insulin/IGF-1 pathway promotes pancreatic cancer cell growth." (PMID 41194999, 2025). "The most upregulated miRNA from HRH1 stimulation, miR-502–3p, was associated with multiple enriched pathways related to insulin resistance, including EGFR tyrosine kinase inhibitor resistance, AGE-RAGE signaling pathway in diabetic complications, and pancreatic cancer." (PMID 40667070, 2025). "Another retrospective cohort study, which included 543,595 diabetic patients, found no increased risk of pancreatic cancer associated with GLP-1RA use compared to basal insulin over a 9-year follow-up period." (PMID 39318780, 2024). "Our work shows that targeting aberrant insulin chromatin looping in pancreatic cancer might provide a therapeutic benefit." (PMID 38927910, 2024). "Additionally, the review elucidates the intricate relationship between pancreatic cancer and glucose levels, emphasizing the role of islets of Langerhans in insulin production." (PMID 38500905, 2024). "Insulin has mitogenic effects and can promote cell proliferation and inhibit apoptosis, which may contribute to the development and progression of pancreatic cancer." (PMID 39405289, 2024). "In our study, unlike research on other cancer types, we expect that GLR, which has a direct relationship with the pancreas that secretes insulin to regulate serum glucose levels, will play a more effective and accurate role in prognostic prediction for pancreatic cancer patients." (PMID 38791922, 2024). "Panc-0813 is an insulin-dependent pancreatic cancer cell line." (PMID 37957639, 2023). "Increased insulin secretions and insulin resistance can occur from diets with a high glycemic index and glycemic load, which may promote the development of pancreatic cancer through their mitogenic and anti-apoptotic effects." (PMID 37842365, 2023). "In unadjusted analyses, the start of an OHG medication (HR, 2.96; 95% CI, 1.93-4.53) or insulin (HR, 5.28; 95% CI, 3.05-9.15) were both associated with pancreatic cancer development when compared to those with no change in use of these medications." (PMID 37117188, 2023). "By stimulating endogenous insulin production, insulin secretagogues increase insulin-like growth factor-1 levels which may promote pancreatic cancer development by interfering with cell metabolism and stimulating cell proliferation." (PMID 37481610, 2023). "PGG acted as an insulin-mimetic compound that damaged pancreatic cancer cells (MiaPaCa2 and Panic-1) and alleviated cachexia in tumor-bearing mice by inhibiting insulin receptor/insulin-like growth factor receptor-1 activity and decreasing glycolytic enzymes in pancreatic cancer cells." (PMID 37375411, 2023). "The mechanisms of PCRD may be centred around the influence of pancreatic tumour-derived exosomes or the ability of β cells to produce insulin and that of other cells to produce, take up or utilize glucose." (PMID 37373351, 2023). "Together with our previous work, we propose that mild suppression of insulin levels may be useful in preventing pancreatic cancer by acting on multiple cell types." (PMID 35189981, 2022). "As a result, pancreatic cancer is often exposed to a high insulin concentration environment." (PMID 35252207, 2022).
pancreatic cancer (continued). "Furthermore, KEGG analysis revealed miRNA up-regulation involvement in (i) insulin signaling pathways, (ii) neurotrophin signaling pathways, and (iii) pancreatic cancer." (PMID 35408847, 2022). "Indeed, euglycemic glucose clamp studies demonstrated that both the insulin sensitivity and beta-cell function were markedly impaired in patients with pancreatic cancer." (PMID 35222270, 2022). "A clear elucidation of the crosstalk between insulin and pancreatic cancer is needed at present." (PMID 35252207, 2022). "In the pancreatic cancer tissue, the tumor-associated fibroblast (TAF) continuously produces IGF-1, which stimulates pancreatic islet beta cells to proliferate and secrete more insulin through a bidirectional microcirculation system in the pancreas." (PMID 35252207, 2022). "The relationship between insulin and pancreatic cancer is complex and important." (PMID 35252207, 2022). "The possible explanation for this could be the discarding through resection of the paraneoplastic effect of pancreatic cancer on glucose metabolism and insulin resistance." (PMID 35625546, 2022). "In the first 20 enriched KEGG pathways of differentially methylated mRNAs between DOK and HOEC cells, 5 pathways were also enriched between SCC-9 and HOEC cells, including phosphatidylinositol signaling system, pancreatic cancer, insulin signaling pathway, colorectal cancer and adherens junction." (PMID 36249071, 2022). "GLP-1 agonist may help reverse insulin resistance induced by pancreatic cancer cells, thus leading to a reduced blood insulin level." (PMID 35252207, 2022). "In addition to promoting the progression of pancreatic cancer, there is a positive correlation between high insulin levels and the progression of colon cancer." (PMID 34485124, 2021). "In addition, this can be related to pancreatic cancer pathways, as the virus seems to induce an increase in insulin production." (PMID 34513323, 2021). "The literature data regarding the involvement of miR-9-5p in PDAC are scarce, but this miRNA is involved in insulin secretion and may represent a prognostic or therapeutic target in pancreatic cancer." (PMID 34440625, 2021). "Nonetheless, it is apparent that miR-29a modulates extracellular IGF-1/IGF-1R signaling in PSCs, and intracellular NRAS expression in pancreatic cancer cells, which indicates a functional role of the molecule in tumor-stromal crosstalk via insulin/IRF -RAS/MAPK signaling mechanism in PDAC." (PMID 32660466, 2020). "Furthermore, the KEGG pathway analysis revealed that the largest subset of differentially expressed genes was associated with pancreatic cancer, and with the VEGF, mTOR, and insulin signaling pathways." (PMID 32843065, 2020). "Taken together, these data strongly support a role of the insulin/IGF axis in pancreatic cancer." (PMID 33101198, 2020). "Insulin is also a highlighted intermediate linking carnitine and pancreatic cancer." (PMID 29342271, 2018). "Pancreatic cancer development could be related to increased insulin levels and higher bioavailability of insulin-like growth factor, in which weight gain, rather than BMI, may play a more essential role." (PMID 30202086, 2018). "We carried out a systematic search of Pubmed and Embase databases for studies published before August 2016, which assessed the associations between anti-diabetic medications (metformin, sulfonylureas, thiazolidinediones and insulin) intake and pancreatic cancer prognosis." (PMID 28977950, 2017). "However, in the analyses stratified by sex, the fasting insulin effect on pancreatic cancer remained increased in men (OR = 2.27, 95% CI = 1.09 to 4.71) but not in women (OR = 0.64, 95% CI = 0.29 to 1.42)." (PMID 28954281, 2017). "Moreover, transgelin-2 partially rescued the growth defect of pancreatic cancer cells caused by SREBP-1 knockdown, suggesting that transgelin-2 is required for SREBP-1-mediated cell growth upon insulin treatment." (PMID 28521289, 2017).